LINC02710 (long independently transcribed non-coding RNA 2710)
Gene: Long non-coding RNA gene on chromosome 11 (46,205,700 to 46,243,757, reverse strand). Ensembl gene ENSG00000255269.
Diseases named in the same sentence as LINC02710 in open-access papers:
LINC02710 is named in the same sentence as 1 disease in open-access papers, as found by Europe PMC text mining. Sharing a sentence is not in itself a finding about the gene and the disease. The quoted sentences say what the papers report.
cancer (1 paper, 2024). A tumor composed of atypical neoplastic, often pleomorphic cells that invade other tissues. "However, the role of LINC02710, AL022328.1 and AC091271.1 in cancer development has not been cleared and needs to be further investigated." (PMID 39723224, 2024).